CA14 (carbonic anhydrase 14)
Description:
Reversible hydration of carbon dioxide.
Synonyms: CAXiV
Tractability: Small molecule: an approved drug acts on it; a structure with a bound ligand is known; a high-quality ligand is known; it belongs to a druggable protein family. Antibody: its Gene Ontology location is reachable by antibodies, with high confidence; UniProt predicts a signal peptide or a membrane-spanning region; the Human Protein Atlas places it where antibodies can reach. PROTAC: its protein half-life has been measured; a small molecule that binds it is known.
Target class: Enzyme; Lyase
Gene: Protein-coding gene on chromosome 1 (150,257,251 to 150,265,078, forward strand). Ensembl gene ENSG00000118298.
Subcellular location: Membrane
Subcellular location (Human Protein Atlas): Plasma membrane
Pathways (Reactome):
Metabolism: Reversible hydration of carbon dioxide
Gene Ontology:
Molecular function: carbonate dehydratase activity; zinc ion binding
Cellular component: membrane; plasma membrane; apical plasma membrane; basolateral plasma membrane
Genetic constraint (gnomAD): Loss-of-function variants: 44 observed, 48.46 expected, observed/expected ratio (o/e) 0.91, 90% interval 0.71 to 1.17. The upper end of that interval is the gene's LOEUF score, 1.17, which puts it in group 5 of 6, group 1 being the genes least tolerant of losing a copy. Missense variants: 364 observed, 396.66 expected, observed/expected ratio (o/e) 0.92, 90% interval 0.84 to 1. Synonymous variants: 141 observed, 150.81 expected, observed/expected ratio (o/e) 0.93, 90% interval 0.81 to 1.08.
Homologues: Orthologues: chimpanzee CA14 (99% identical), macaque CA14 (96% identical), dog CA14 (86% identical), guinea pig CA14 (86% identical), rabbit CA14 (85% identical), mouse Car14 (84% identical), pig CA14 (84% identical), rat Car14 (79% identical), tropical clawed frog ca14 (50% identical), zebrafish ca14 (48% identical), Caenorhabditis elegans cah-5 (29% identical), Drosophila melanogaster CAH4 (25% identical), and 7 more. Paralogues in human: CA12 (41% identical), CA9 (38% identical), CA6 (32% identical), CA4 (29% identical), CA13 (28% identical), CA7 (28% identical), CA5A (27% identical), CA2 (27% identical), CA1 (26% identical), CA3 (26% identical), CA5B (26% identical), CA8 (25% identical), and 2 more.
Diseases named in the same sentence as CA14 in open-access papers:
CA14 is named in the same sentence as 16 diseases in open-access papers, as found by Europe PMC text mining. Sharing a sentence is not in itself a finding about the gene and the disease. The quoted sentences say what the papers report.
melanoma (4 papers, 2018 to 2025). A malignant, usually aggressive tumor composed of atypical, neoplastic melanocytes. "By machine learning algorithms, we identified 6 key CRGs (ABCC2, CA14, EGR3, FBXW7, LDHB, and PSEN2) closely associated with melanoma." (PMID 39213172, 2024). "Compared to normal skin tissues, 4 key CRGs (ABCC2, CA14, LDHB, PSEN2) were significantly upregulated while 2 key CRGs (EGR3, FBXW7) were significantly downregulated in melanoma tissues." (PMID 39213172, 2024). "Among them, 4 key CRGs (ABCC2, CA14, LDHB, PSEN2) were significantly upregulated and 2 key CRGs (EGR3, FBXW7) were significantly downregulated in melanoma tissues." (PMID 39213172, 2024). "Finally, by comparing the feature genes identified by the three machine learning approaches, six common key CRGs were identified as melanoma-related key CRGs, including ABCC2, CA14, EGR3, FBXW7, LDHB, and PSEN2." (PMID 39213172, 2024).
breast carcinoma (3 papers, 2018 to 2024). "Studies have found that overexpression of CA14 is related to the development and progression of tumors such as breast cancer, prostate cancer, and non-small cell lung cancer." (PMID 39213172, 2024).
prostate carcinoma (3 papers, 2023 to 2025). A carcinoma that arises from epithelial cells of the prostate gland. "We identified a novel gene risk panel comprising six genes (SSTR1, CA14, HJURP, KRTAP5-1, VGF, and COMP) for prostate cancer risk classification." (PMID 40592939, 2025).
cataract (1 paper, 2025). Partial or complete opacity of the crystalline lens of one or both eyes that decreases visual acuity and eventually results in blindness. "The decline of CA14 in the aging lens may also be linked to the putative role of zinc in cataractogenesis, as CA14 levels decline in rat retinas with zinc deficiency; and zinc-deficient diet causes cataracts in fish." (PMID 40649110, 2025).
tumor (1 paper, 2025). "Moreover, mRNA expressions of CA14, RPE65, IGSF1, SLC18 A2 and CPNE6 were significantly lower in PCa samples compared to benign samples, while HJURP, COMP, KRTAP5-1, VGF, SSTR1, LINC01612, NAALADL2-AS2, AMH and ARHGDIG were elevated in tumor samples (p < 0.05)." (PMID 40592939, 2025).
CA14 also shares sentences with these, for which no sentence is quoted: cancer (3 papers); cardiac hypertrophy (1); dilated cardiomyopathy (1); glioma (1); liver fibrosis (1); macular edema (1); non-small cell lung carcinoma (1); prostate hyperplasia (1); retinal degeneration (1); rheumatoid arthritis (1); Zinc deficiency (1).